MICA (MHC class I polypeptide-related sequence A)
Diseases named in the same sentence as MICA in open-access papers (continued):
Sharing a sentence is not in itself a finding about the gene and the disease.
tumor (continued). "The therapeutic effect of immunization with BLS-MICA resulted in significant inhibition of the growth of MICA-expressing tumors by binding excess sMICA molecules, tumor elimination by ADCC, and prevention of tumor escape." (PMID 34835294, 2021). "Released soluble MICA (sMICA) and soluble MICB (sMICB) can thereafter bind to NKG2D and induce its down-modulation and degradation, subverting NKG2D-dependent effector functions of NK cells and facilitating tumor immune escape." (PMID 34394116, 2021). "Shedding of the major histocompatibility complex (MHC) class I chain-related protein A and B (MICA/B), the ligands of NKG2D that can be expressed on tumor cells, is one of the most characterized mechanism responsible for the impaired NKG2D recognition and subsequent tumor immune evasion." (PMID 33262461, 2021). "The best characterized NK cell-activating receptor playing a prominent role in tumor immunosurveillance is NKG2D, whose ligands (MICA, MICB, ULBP1-6) are frequently induced on the surface of tumor cells in response to different types of cellular stress typical of a neoplastic transformation." (PMID 31948072, 2020). "Interestingly, Schrambach and colleagues revealed MICA and MICB mRNA transcripts in healthy organ tissue as well as various tumours, suggesting regulation of surface NKG2DL expression is not solely controlled at a transcriptional level." (PMID 33352921, 2020). "MICA/B work as the two ligands of NKG2D, express at the surface of tumour cells." (PMID 31642585, 2020). "Some studies have shown that the existence of soluble MICA/B in the serum could degrade and internalize NKG2D expressed on NK or CD8+ T cells leading to tumor escape from immune response." (PMID 32645836, 2020). "Shed soluble MICA (sMICA) is also present in plasma of MICAgen mice but affects neither surface NKG2D expression of circulating NK cells nor their functional recognition of MICA-expressing tumor cells." (PMID 32582150, 2020). "The metastasis-associated miR-10b directly targets the 3′-UTR of MICB, but not MICA, and downregulates its expression in several cancer cell lines, impairing the ability of NK cells to recognize and eliminate tumor cells." (PMID 32316552, 2020). "Furthermore, MICA and MICB shedding from a range of tumour cell lines was attributed to either or both ADAM10 and ADAM17, but the regulation of this process was different depending on the cancer cell lines tested." (PMID 33352921, 2020). "In addition, it was demonstrated that tumor cells released the NKG2D ligands, MICA and MICB, in a soluble form by proteolytic shedding from the tumor cell surface by metalloproteases and protected tumor cells from cytolysis if they were NKG2DL-positive." (PMID 30845699, 2019). "Indeed, CEACAM1 can down-regulate MICA/B and ULBP1 from the tumor cell surface thus influencing their immunogenicity." (PMID 30871206, 2019). "As shown in the representative plot of the FACS analysis, tumor exosomes expressed, even if at low levels, MICA/B, but not ULPB-1." (PMID 31186484, 2019). "ULBPs and MICA/B are NKG2D ligands involved in enhancing killing by cytotoxic lymphocytes such as αβ and γδ T-cells and NK cells, so, their upregulation on tumour cells is relevant to the immune response to tumour." (PMID 30733494, 2019). "PD-L1 is a direct target gene of the BET family member Brd4, and BET inhibition by JQ-1 has been found to enhance anti-tumor immunity by suppressing the PD-L1 expression on tumor cells and antigen-presenting cells but also through upregulation of NKG2D ligand MICA on tumor cells." (PMID 29593742, 2018). "Similarly, in cancer patients, the presence of MICA- and ULBP1-expressing myeloid cells in blood and tumor correlated with reduced NKG2D expression on NK cells." (PMID 29740438, 2018).
tumor (continued). "We describe the conditions for detection of MICA in exosomes and prove, for the first time using both techniques, the co-existence in one vesicle of exosomal markers (the tetraspanins CD9, CD63 and CD81) and an endogenously expressed tumour-derived antigen." (PMID 29720199, 2018). "However, tumor cells can release soluble forms of NKG2D ligands and elevated levels of MICA/B and ULBP2 have been detected in sera of patients with various epithelial and hematopoietic malignancies." (PMID 30298063, 2018). "The correlation of lobular MICA and CD56 levels strengthens a hypothesis in which MICA and CD56+ NK cells function together within an anti-tumor cytotoxic system." (PMID 29090365, 2018). "However, given the lack of direct association between these markers and an eventual cancer diagnosis, further studies are needed to confirm a functional role of MICA and CD56+ NK cells in tumor immunosurveillance." (PMID 29090365, 2018). "In addition, several studies have reported that the secretion or expression of MMPs by tumor cells (including the secreted MMP-2, MMP-9 and the membrane type MMP-14) can lead to the shedding of MICA/B at their surface." (PMID 28423623, 2017). "MICA releases soluble proteins produced on the surface of tumor cells, inducing negative modulation of NKG2D and facilitating tumor cell escape from NK cell killing." (PMID 28484463, 2017). "Furthermore, miR-519a-3p impaired tumor cell killing by natural killer (NK) cells via downregulation of the NKG2D ligands ULBP2 and MICA on the surface of tumor cells that are crucial for the recognition of these tumor cells by NK cells." (PMID 28771222, 2017). "Indeed, MICA, one of the major ligands for NKG2D, is often overexpressed in many tumor tissues from patients with epithelial tumors and some primary leukemia cells." (PMID 26909862, 2016). "We found a significant upregulation of MICA and PVR/CD155 mRNA and cell surface expression by lenalidomide and pomalidomide; accordingly, NK-cell degranulation was enhanced upon interaction with IMiDs-treated tumor cells." (PMID 26269456, 2015). "Like HLA, MICA antigens are polymorphic and expressed on endothelial cells, dendritic cells, fibroblasts, epithelial cells, and many types of tumor cell; MICA antigens are not expressed on peripheral blood lymphocytes." (PMID 26024219, 2015). "To investigate whether an inhibition of HSF1 can explain the effects of NZ28 on the NK cell-mediated cytotoxicity and MICA/B expression, we knocked down HSF1 in H1339 tumor cells by RNA interference." (PMID 25854583, 2015). "Metalloproteases are known to release MICA (soluble MICA, sMICA) and other NKG2D ligands from the cell surface resulting in a downregulation of NKG2D expression on CD8+ T cells which has been demonstrated as a route of immune evasion of tumor cells." (PMID 26646698, 2015). "Treatment of H1339 and MDA-MB-231 tumor cells with 100 nM NVP-AUY922 did not affect the MICA and MICB cell surface density (MFI) (lower part)." (PMID 25854583, 2015). "Our data demonstrate that Hsp90 inhibition alters neither the MICA/B surface density nor the sensitivity of the tumor cells to NK cell-mediated lysis." (PMID 25854583, 2015). "However, a stronger induction of P21 and MICA expression was observed upon treatment with MTA, the latter being a gene involved in the activation of the anti-tumor immune response." (PMID 26536461, 2015). "Repasky’s group showed that heating tumour cells in vitro at 39.5 °C for 6 h increased surface expression of MICA, an NKG2D ligand, but not MHC class I, making the cells more sensitive to lysis by natural killer (NK) cells." (PMID 25430985, 2014). "Besides, another important finding of the present study is that GRP78, a marker of UPR, was significantly related with tumor TNM stage and negatively correlated with MICA/B expression level in HCC tissues." (PMID 25228093, 2014).
tumor (continued). "In rodents, RAE-1, MULT-1, and H-60 are upregulated in tumor cells but not normal cells, similar to MICA and MICB in humans." (PMID 24723923, 2014). "Furthermore, as described for Vγ9Vδ2 T cells, recognition of MICA, MICB, or ULBP expressed on cancer cells by human Vγ1δ1 T lymphocytes can trigger or increase their cytolytic activity against tumor cells that express NKG2D ligands." (PMID 25538706, 2014). "For instance, stroma-derived factors in the tumor microenvironment, in particular TGF-β, display an immunosuppressive activity on most anti-tumor immune effectors, and an indirect immunosuppressive effect via the inhibition of MICA transcription." (PMID 24715892, 2014). "The other molecule that is up-regulated by the drugs is type II transmembrane protein NKG2D, which recognizes MHC class I chain-related molecules (MICA and MICB), as well as UL16-binding proteins (ULPBs) that are expressed on stressed cells, including tumor cells." (PMID 24169587, 2013). "The MHC class I chain-related (MIC) molecules, MICA and MICB, as well as the UL16-binding proteins (ULBPs), expressed on the surface of a broad range of carcinomas and some hematopoietic malignancies, play an important role in tumor surveillance by NK cells." (PMID 24400010, 2013). "On tumor or stressed cells, this type II transmembrane receptor recognizes ligands, such as UL-Binding Proteins (ULBPs) and MHC class I Chain-related protein A (MICA) and B (MICB), all related to the MHC class I molecules." (PMID 23493799, 2013). "We also discovered that the MICA protein was not expressed on the surface of primary tumor cells but shed as soluble (s) molecule in serum of NB patients." (PMID 23805414, 2013). "The MICA and MICB proteins are ligands for Natural Killer (NK) group 2, member D (NKG2D) activating receptors on NK cells, CD8+ T cells, and γδ T cells important for the immune-targeted destruction of tumour cells." (PMID 22461998, 2012). "Moreover, TSA, SAHA, VPA, and sodium butyrate were also found to increase the expression of the MHC class I-related chain A (MICA) and chain B (MICB) on tumour cells." (PMID 22461998, 2012). "The median and mean serum MICA levels in 15 patients with tumor stages I-III were 144 and 437 ± 40 pg/ml respectively, compared to 231 and 1325 ± 69 pg/ml in 46 patients with a stage IV tumor." (PMID 21605422, 2011). "It would be interesting to determine if this behavior is a more general property of MICA- and MICB-producing cells by evaluating whether virus-infected and tumor cells known to secrete MICA and MICB also express NKG2D." (PMID 21477352, 2011). "Moreover, the tumor-derived soluble MICA induced endocytosis and degradation of the cognate activatory receptor NKG2-D on tumor-infiltrating lymphocytes, impairing their activation." (PMID 21712991, 2011). "The secretion of MICA and MICB by cancer cells has been suggested as a mechanism for tumor cell immune escape through the saturation of NKG2D receptors on cytotoxic cells, thus abrogating their ability to recognize tumor cells." (PMID 21477352, 2011). "We can further speculate that malignant cells not only can deplete MICA and MICB in situ to avoid immune recognition, but they can also use the stress factors as endogenous tumor growth factors." (PMID 21477352, 2011). "Statistical analyses revealed that MICA levels in patients with tumor stages I-III were not significantly lower than those with a stage IV tumor (p = 0.178)." (PMID 21605422, 2011). "Another study used immunohistochemistry to determine that tumor from 82 ovarian cancer patients showed expression of MICA, MICB, and ULBP-2, while none of these molecules was expressed by normal ovarian epithelium." (PMID 20350313, 2010). "However, in late-stage HCC cells in co-culture models, MICA induces a decrease in EHHADH expression, leading to macrophage conversion to the anti-inflammatory M2-like phenotype, which may contribute to tumor progression." (PMID 40723248, 2025).
tumor (continued). "However, in late-stage HCC, MICA induces a decrease in EHHADH expression, leading to macrophage conversion to the anti-inflammatory M2-like phenotype, which may contribute to tumor progression." (PMID 40723248, 2025). "Additionally, RCC tumor cells exhibited universal and elevated expression of NK cell-activating ligands, including MHC class I chain-related protein A and B (MICA/B) and UL16-binding proteins (ULBPs) (ligands for NKG2D), as well as CD112 and CD155 (ligands for DNAM-1)." (PMID 40885188, 2025). "Each cell line overexpresses αvβ6, required for Ad5NULL-A20 transduction, and EGFR and MICA (including other NKG2D ligands) required for BICA activation, therefore possess the required characteristics to demonstrate T cell activation and tumor cell lysis by CD3-BICA." (PMID 40741595, 2025). "Notably, tumor microenvironment analysis proposed a critical mechanism: In CRC cells, membrane-bound MICA (mMICA) is cleaved and hydrolyzed by the ADAMs family, which may drive the proteolytic shedding and generate a large amount of soluble MICA (sMICA)." (PMID 40726981, 2025). "The near-exclusive expression of RAET1L (ULBP6) in malignant cells within the tumor microenvironment distinguishes it from nontumor-specific NKG2DLs such as MICA/B, which may translate to an improved therapeutic window for ULBP6-targeting therapies." (PMID 40116579, 2025). "Furthermore, a transgenic mouse model with systemic MICA expression reported suppression of NKG2D-mediated anti-tumor immunity, whereas soluble MICA in the serum did not affect NKG2D expression in non-transgenic mice." (PMID 40243581, 2025). "Moreover, upregulation of MHC class I chain-related polypeptide A (MICA), which serves as a ligand activating NK group 2D (NKG2D) receptor on NK cell and T cell subpopulations as an OV gene engineered transgene, was observed in tumor cells." (PMID 39055561, 2024). "Likewise, MICA/B and ULBP1 were abundantly expressed, with more than 75 and 57% of the bone metastatic samples showing the expression of these markers in more than 50% of the tumor cells, respectively." (PMID 37134157, 2023). "The released soluble MICA (sMICA) can bind to NKG2D and induce the downregulation and degradation of NKG2D in NK and T cells, reducing NKG2D-dependent effector functions, resulting in decreased cytotoxicity of these immune effector cells and facilitating tumour immune evasion." (PMID 37784183, 2023). "Interestingly, the response to APTO253 was restricted to tumor cells, whereas lymphocytes from healthy donors did not up-regulate MICA or KLF4." (PMID 37143070, 2023). "Since it has been demonstrated that tumor-derived soluble MICA can negatively impact NK cell cytotoxicity by modulating the NKG2D pathway, we investigated if high serum levels of soluble MICA in patients with PD was correlated with a downregulation of NK activation and cytotoxic markers." (PMID 36991390, 2023). "Altogether, these data suggest that high serum MICA levels in patients with PD could be correlated with downregulation of NK activation and cytotoxic markers, impairing the NK-mediated ADCC triggered by NEO-201 against tumor cells." (PMID 36991390, 2023). "Interestingly, disintegrin and metalloproteinase domain-containing 10 (ADAM10) was upregulated in senescent tumor cells, and combined treatment with the ADAM10 inhibitor GI254023X and chemotherapeutic drugs inhibited MICA/B secretion and enhanced recognition and killing by NK cells." (PMID 35309907, 2022). "Besides TCR-associated antigen recognition, Vγ9Vδ2 T cells also express NK receptors including NKG2D and DNAM1, which recognize MHC class I chain-related molecules (MICA, MICB), ULBP-binding proteins (ULBPs) and Nectin-like-5 that are broadly expressed on tumor cells." (PMID 35747139, 2022).
tumor (continued). "The increase of soluble MICA by the action of MICA-shedding proteases has been reported in several patients with HCC, impairing the action of NK cells and leading to the defective recognition of the tumor, and TGF-β may be playing a role in this process." (PMID 34209646, 2021). "Interestingly, MHC class I chain-related molecules (MICs), such as MICA and MICB, are proteins expressed in the membrane of tumor cells that bind to the C-type lectin-like stimulatory immune receptor NKG2D in NK cells and CD8+ T cells, activating its cytotoxic effects." (PMID 33946818, 2021). "Although, tumor cells might still manage to escape the immune surveillance by down-regulating NKG2D via increased TGF-β secretion or decreased expression of its ligands, such as major histocompatibility chain-related protein A (MICA)." (PMID 34566989, 2021). "Of note, it has been shown that aggressive tumors, such as metastatic PC, cleave MICA/B from the membrane of NK and CD8+ T cells, release the soluble form (sMIC) into the plasma, and downregulate the NKG2D receptor from the immune cells, thereby promoting immune suppression and tumor escape." (PMID 33946818, 2021). "Similar to the NKG2D ligands MICA and MICB, the NKp30 ligand B7-H6 could be cleaved from the surface of tumor cells and released as soluble B7-H6, thus preventing the NKp30-mediated recognition of tumor cells." (PMID 34203391, 2021). "In addition to PD-L1 upregulation, suppression of NK group 2D (NKG2D)-activating ligands (including ULBP1, ULBP2, ULBP3, MHC class I chain-related molecules A and B, MICA and MICB) may represent another way of tumor escape from NKCC." (PMID 34830209, 2021). "It is important to note that the activity of NK cells is inhibited by the immunosuppressive factors such as TGF-β, IL-6, IL-8, IFN-γ, MICA,B released in TME and the differences between the CSCs and other tumor cells secretomes may also inhibit cytotoxic NK cells more strongly." (PMID 34923966, 2021). "Although these approaches have shown some preliminary interesting effects, compared to anti-MICA Ab-based strategies, they only promote the bridging between NK cells and tumor cells and do not target, for example, suppressive sMICA, which limits their competitive landscape." (PMID 34394116, 2021). "Using 2D and 3D biological models, we confirm SCI-101 sustains GBM cytotoxicity 72 h after drug removal and induces cell surface MICA/B protein and ULBP mRNA up to 200% in residual tumor cells compared to the naked drug alone without augmenting the shedding of MICA/B, in vitro." (PMID 34926577, 2021). "In the context of tumor-immunosurveillance, pADAM10 has not only been identified as sheddase of canonical substrates on platelets, but also to be involved in cleavage of the stress-induced NKG2D ligands (NKG2DL) MICA, MICB and ULBP2 from the surface of tumor cells." (PMID 32117229, 2020). "Indeed, MICA/B α3 domain–specific mAb significantly increased the density of the stimulatory MICA and MICB ligands on the surface of tumor cells, reduced MICA shedding, and induced NK cell–mediated tumor immunity." (PMID 32283827, 2020). "Given that MICA and MICB are lost from the tumour cell surface in a platelet-dependent manner, we hypothesised a role for the platelet in promoting the release of soluble NKG2D ligands into the microenvironment of the cloaked tumour cells." (PMID 30908480, 2019). "We next asked whether the tethering MICA-ICs on Fc receptor-bearing NK cells is able to activate NK cells in the absence of tumor cells." (PMID 31387641, 2019). "In contrast, upregulation of MICA and MICB (MHC class I polypeptide-related sequence B) gene expression has been reported in CaCo-2 colon carcinoma cell line upon oxidative stress, an effect that could strengthen NK cell recognition and tumor cell elimination." (PMID 31535086, 2019).